PRDM1 (PR/SET domain 1)
Diseases named in the same sentence as PRDM1 in open-access papers (continued):
Sharing a sentence is not in itself a finding about the gene and the disease.
tumor (continued). "Of the promoters gaining methylation in our sample, many have already been shown to have tumour suppressor activity, including RORa, FAN1, PRDM1, CYGB, L3MBTL4, EPB41L3, with ZNF471 and ZNF671 being specifically silenced by methylation." (PMID 31357948, 2019). "SMYD2, EZH2, and SUV420H2 were up‐regulated and SETD7, PRDM1, PRDM8, PRDM6, and PRDM5 were down‐regulated in tumor." (PMID 30984543, 2019). "Some of these switches occur in known tumor drivers, including PPARG, CCND3, RALGDS, MITF, PRDM1, ABI1 and MYH11, for which the switch implies a change in the protein product." (PMID 25578962, 2015). "Moreover, PRDM1 perturbation altered inferred cellular trajectories, opposing the transcriptional shift toward an adaptive NK-associated state, suggesting that PRDM1 may contribute to maintenance of aNK-associated identity and functional features in the CRT-conditioned tumor microenvironment." (PMID 42110212, 2026). "The proportion changes of cNK cells and ILC1s in Prdm1 cko mice was similar with the no tumor-burden condition, while the number of both cNK cells and ILC1s have significant decreased in tumor-bearing liver." (PMID 39133873, 2024). "Knockout of PRDM1 and NR4A3 improved the anti-tumor response by increasing the generation of long-lived memory cells, counteracting exhaustion in tumor-infiltrating CAR T cells, and enhancing the overall anti-tumor response." (PMID 38693513, 2024). "Dual knockout of PRDM1 and NR4A3 skewed CAR T cell phenotypes away from TIM-3+CD8+ and toward TCF1+CD8+ to counter exhaustion of tumor-infiltrating CAR T cells and improve antitumor responses, effects that were not achieved with PRDM1 and NR4A3 single knockout alone." (PMID 36350986, 2022). "PRDM1/BLIMP1 overexpression inhibits cell-intrinsic cell growth while promoting tumor cell immune evasion by up-regulating PD-L1 and dampening CD8+ T cell anti-tumor immune response simultaneously." (PMID 36509766, 2022). "The Prdm1 overexpression group showed no visible difference in tumor proliferation and survival time compared with the control group." (PMID 36509766, 2022). "Whereas AAVS1, PRDM1, and NR4A3 single KO CAR T-cells controlled tumor growth in about 50% of mice in the high-burden PC3-PSMA cell xenograft model, PRDM1/NR4A3 double KO CAR T-cells successfully suppressed tumor growth in all treated mice, in association with overall prolongation of survival." (PMID 36350986, 2022). "To evaluate the effector functions of PRDM1 KO CAR T-cells in the setting of repetitive antigen exposure, we first assessed cytokine concentrations 24 hours after the first and fifth rounds of in vitro PC3-PSMA tumor cell stimulation." (PMID 36350986, 2022). "We used the GEPIA2 database to obtain PRDM1 gene expression data of tumor samples and corresponding normal pancreatic tissues, thus detecting differences in PAAD of PRDM1 compared to normal tissues." (PMID 35607327, 2022). "However, when PRDM1 KO was combined with NR4A3 KO, CAR T-cells induced rapid tumor clearance and durable antitumor efficacy." (PMID 36350986, 2022). "To elucidate the mechanism by which PRDM1 KO CAR T-cells fail to maintain effector function following chronic antigen stimulation, we performed bulk RNA-seq on CAR T-cells harvested after several rounds of tumor challenge." (PMID 36350986, 2022). "In univariate analysis, high expression of PRDM1 in tumor samples correlates with poor prognosis in LAML (p = 0.001), LGG (p < 0.001), PAAD (p = 0.008), UVM (p < 0.001); while high expression of PRDM1 correlates with favorable prognosis in KIRC (p = 0.002), SKCM (p < 0.001) and THCA (p = 0.033)." (PMID 33384601, 2020). "The microRNA miR-223 mediates the downregulation of PRDM1 in ENKTL and evaluation of this tumor suppressor may offer a predictor of overall survival." (PMID 32098335, 2020).
tumor (continued). "As PRDM1 is one of the candidate genes found within the frequently deleted chromosomal region 6q21-6q25 in ENKTL, this raises a reasonable consideration of its potential tumor suppressor role in NK neoplasms as well." (PMID 30935402, 2019). "Finally, miR-30 is described as a marker of the germinal centre involved in the pathogenesis of DBLCL where it exerts its anti-tumor activity by targeting BCL6 and PRDM1." (PMID 25232701, 2014). "Among the rich screen results, several intriguing genes (BATF, PRDM1, and TOX) and signalling cascades (JAK-STAT and NF-κB pathways) have been identified to extensively engage in multiple branches of T cell anti-tumour responses and might be leveraged to advance cancer immunotherapies." (PMID 38581063, 2024). "Additionally, three genes (PRDM1, IFI27 and SIGLEC15) were highly expressed in tumor tissues but were also favorable prognostic factors, suggesting a paradox: they promote carcinogenesis but inhibit tumor progression." (PMID 38287330, 2024). "However, direct evidence supporting the impact of Prdm1 on NK cell anti-tumor capabilities is still lacking." (PMID 39133873, 2024). "The proinflammatory cytokine release occurs due to positive regulatory (PR)/SET domain 1 (PRDI-BF1 or PRDM1) or B-lymphocyte-induced maturation protein-1 (BLIMP-1) upregulation in TIME monocytes/macrophages without their death to support tumor growth via promoting M2 polarization." (PMID 37380989, 2023). "Thus, Prdm1 fails to impede tumor proliferation in immunocompetent mice but impairs tumor progression in immunodeficient mice." (PMID 36509766, 2022). "However, no obvious differences were observed between the Prdm1 or sgPrdm1 groups and their corresponding controls in terms of tumor size and OS." (PMID 36509766, 2022). "In addition, we found that the expression levels of T-cell exhaustion-related genes including CD40, GRB2, MKI67, NFATC3, PRDM1, TCF7, and TGFB1 were significantly higher, while those of CXCR5 and TOX were significantly lower after tumor recurrence (all p < 0.05)." (PMID 34305618, 2021). "Results revealed that tumor volume and weight were significantly enhanced in the presence of oe-KPNA2, whereas KPNA2 and c-FOS expression was upregulated and PRDM1 expression was downregulated accompanied by accelerated cell proliferation and suppressed cell apoptosis." (PMID 33731128, 2021). "PRDM1 mutations occurred in patients with plasmablastic lymphoma; interestingly, in this rare neoplasm, PRDM1 genetic alterations did not impair terminal B-cell differentiation, but contributed to the oncogenicity of MYC, which is usually dysregulated by translocation or amplification." (PMID 32290321, 2020). "Importantly, genes co-expressed with SLC16A7/MCT2 in human tumours also clustered in oncogenic-related pathways (e.g. PI3K, EGFR, KRAS) and effectors of these signalling pathways were found to bind at the SLC16A7/MCT2 gene locus (e.g. MYC, EGR1, PRDM1)." (PMID 26035357, 2015). "Despite lack of improved tumor control over AAVS1 KO CAR T-cells, PRDM1 KO CAR T-cells exhibited enhanced in vivo expansion and persistence." (PMID 36350986, 2022). "Together, these results suggest that, despite improvements in expansion and persistence, PRDM1 KO alone is not sufficient to potentiate robust and sustained CAR T-cell antitumor efficacy in aggressive tumor models." (PMID 36350986, 2022). "However, genetic deletion of PRDM1 alone resulted in only marginal enhancement of CAR T-cell efficacy against B-cell leukemia and completely failed to rescue CAR+ tumor-infiltrating lymphocyte (TIL) function in animal models of high tumor burden." (PMID 36350986, 2022).
infection (71 papers, 2013 to 2026). The state of being infected such as from the introduction of a foreign agent such as serum, vaccine, antigenic substance or organism. "As anticipated, the data showed that Ifng-lamina association was similar between WT and Prdm1−/− cells for both types of infection." (PMID 39083377, 2024). "Similarly, depletion of KDM6A in mice treated with Listeria monocytogenes expressing OVA enhanced immune response after secondary infection by reducing CTLs formation through H3K27me3 regulation on Prdm1, which encoded Blimp1 and played essential roles in the development of CD8+ memory T cells." (PMID 37353521, 2023). "We observed a significant correlation between Areg and both Hif1a and Prdm1 expression after infection, especially in Treg cells, and thus tested their impact on Areg induction following LCMV infection." (PMID 41094201, 2025). "A similar reduction in infection burden was seen in monolayers treated with an siRNA that knocked down Prdm1 expression." (PMID 40497734, 2025). "During acute infection, Blimp-1 conditional knockout (KO) mice (Prdm1−/−) exhibit sustained PD-1 expression in 8-dpi virus-specific CTLs relative to wild-type (WT) mice." (PMID 39083377, 2024). "Instead, four IFN expression inhibitory genes (AHR, DUSP1, HES1, and PRDM1) were significantly up-regulated by WT infection." (PMID 37513744, 2023). "In acute LCMV infection, despite a reduction in cytotoxic molecule production, the cytolytic activity of virus-specific PRDM1 KO CD8+ T-cells was marginally affected and both wild type and PRDM1 KO CD8+ T-cells successfully cleared the infection." (PMID 36350986, 2022). "Due to the long coding region of PRDM1, the infection efficiency in primary T cells is very low, it is difficult to acquire a sufficient number of PRDM1-overexpression CD4+ or CD8+ T cells for further multiomics sequencing." (PMID 35572579, 2022). "Of note, Prdm1 was not only more highly induced in WT compared to Adrb2-/- cells at day 4 post-infection, it was also selectively included in genes constituent to WT path G, but not in Adrb2-/- path E." (PMID 35944008, 2022). "A high expression level of Prdm1 in the neonatal intestinal epithelium and its absence in adult intestinal epithelium were consistent with a higher infection burden in the neonatal enteroids." (PMID 34488445, 2021). "Among all DEGs, PRDM1 was the most induced gene (~33-fold higher) after infection, and FOS was the fifth-most-induced gene in this study." (PMID 34578166, 2021). "Complementarily, IEC4.1 cells with forced expression of Prdm1 resulted in an increase of the infection burden and a decrease in the expression of those defense genes in infected cells in response to IFN-γ stimulation." (PMID 34488445, 2021). "ALI mice presented an increase in PRDM1 expression in the lung tissues following infection of lentivirus expressing oe-PRDM1." (PMID 33109608, 2020). "Interestingly, a study on Pilchard orthomyxovirus (POMV) infection in Atlantic salmon (Salmo salar) suggested that PRDM1 plays a central role as a key regulatory factor during the infection with POMV." (PMID 39212852, 2024). "Alterations in PRDM1 expression may influence memory T-cell production and as a result alter the ability upon re-infection to mount an immune response." (PMID 35328504, 2022). "Due to the absence of Prdm1 in adult intestinal epithelial cells, such inhibitory cross-linking is not available in adults and may contribute to associated resistance of infection to Cryptosporidium." (PMID 34488445, 2021). "In contrast, WT infection induced significantly higher expressions of genes that negatively regulate type I IFN expression, such as AHR, DUSP1, HES1, and PRDM1, compared to the mutant-infected cells." (PMID 37513744, 2023). "We found that the transcript levels for Zbtb32 were substantially elevated in Prdm1-/- CD44hi CD8+ T cells isolated at days 8 and 14 post-LCMV-Armstrong infection compared to WT controls." (PMID 28827827, 2017).
infection (continued). "Upon infection with H. hepaticus, the absence of Prdm1 or Maf in T cells resulted in mild to moderate pathology, while the absence of both transcription factors resulted in severe pathology." (PMID 38609547, 2024). "Knockdown of Prdm1 in IEC4.1 cells resulted in enhanced antimicrobial activity against C. parvum infection induced by IFN-γ, with a significant further decrease in the infection burden and a further increase in the expression of defense genes, including Nos2, Ido1, and Csf2." (PMID 34488445, 2021). "WT (Prdm1+/+ROSA26-Cre-ERT2; Thy1.1/1.1) and Blimp1–/– (Prdm1fl/fl ROSA26-Cre-ERT2; Thy1.1/1.2) naïve P14 CD8+ T cells were co-transferred into B6 mice and tamoxifen administration began two days before infection with VacV (+/- Ag) on the left and right ear skin." (PMID 37402742, 2023). "Moreover, STAT5A and PRDM1, two key regulators of Tfh cell development, were not upregulated under HIVYu2b infection in memPD-1pos-derived TfhD3." (PMID 34984326, 2022). "Similarly, we found no upregulation of Bcl6, PRDM1, and ZBTB7B (Thpok) in memPD-1neg-derived TfhD3 cells under HIVYu2b infection." (PMID 34984326, 2022).
cancer (68 papers, 2012 to 2026). A tumor composed of atypical neoplastic, often pleomorphic cells that invade other tissues. "In cancer survivors who received radiotherapy for Hodgkin lymphoma, the risk of second cancer is associated with single nucleotide polymorphisms at rs4946728 and rs1040411 related to the PRDM1 gene." (PMID 40906139, 2025). "Given that CAR T-cell dysfunction can be induced by prolonged exposure to cancer cells due to low cytotoxic activity, we investigated how the impaired cytotoxicity of PRDM1 KO CAR T-cells affects regulation of exhaustion-associated transcription factors." (PMID 36350986, 2022). "Ribosomal dysfunction-activated ERK1/2 was notably attenuated by PRDM1 depletion via its shRNA, indicating the positive regulation of ERK1/2-linked signaling pathways by PRDM1 in response to ribosomal dysfunction in cancer cells." (PMID 33972671, 2021). "Since PRDM1 can induce components involved in IGFR-linked pathway, overexpression of PRDM1 displayed saturated levels of IGF-elevated cancer stemness." (PMID 33972671, 2021). "Based on this association, PRDM1-mediated modulation was evaluated as a platform signaling of cancer cellular responses under the ribosomal dysfunction." (PMID 33972671, 2021). "PRDM1-deficient cancer cells displayed marginal expression of CDX2 in response to ribosomal dysfunction, indicating a positive regulation of CDX2 by PRDM1." (PMID 33972671, 2021). "The transcriptional activity of PRDM1 is essential for the differentiation and maintenance of long-lived plasma cells, whose downregulation has been associated with several types of cancer." (PMID 32985591, 2020). "This increased NFAT signaling may be attributed to prolonged exposure of PRDM1 KO CAR T-cells to cancer cells in association with the delayed killing kinetics we demonstrated." (PMID 36350986, 2022). "Intriguingly, we found that the protein expression levels of MECOM, PRDM5, PRDM10, and PRDM11 were generally higher in UCEC tissue compared to normal tissue, while the expression of PRDM1 was diminished in cancer tissue." (PMID 39468462, 2024). "Although Prdm1 did not affect the killing function of cNK cells in an in vivo cytotoxicity model, a significant increase in cancer metastasis was observed in Prdm1 knockout mice." (PMID 39133873, 2024). "Here, we show the role of PRDM1/BLIMP1 in the regulation of immune molecules expressed by HCC cells with respect to cancer immune evasion." (PMID 36509766, 2022). "PECAM1 and PRDM1 immune gene expression was negatively related to the non-cancer recurrence-adjusted radiomic features of LHH_glszm_LGLZE and LHH_ngtdm_Contrast." (PMID 35454802, 2022). "Functionally, T cell-mediated cancer cell-killing assays and subcutaneous and orthotopic models demonstrated that PRDM1 overexpression in HCC cells dampens T cell-induced cytotoxicity by upregulating tumoral PD-L1 expression." (PMID 36509766, 2022). "In contrast, PRDM1-depletion increased the chemosensitivity to 5-FU in cancer spheroids, indicating that CRC stemness was positively associated with PRDM1-mediated chemoresistance." (PMID 33972671, 2021). "PRDM1, also known as Blimp-1, is a transcriptional repressor, and its upregulation in cancer is known to dysregulate other proteins." (PMID 34367349, 2021). "The authors further suggest PRDM1 promotes cancer cell stemness and survival, altogether providing insights into environmental stress-mediated signaling in CRC." (PMID 33972671, 2021). "Since cancer stemness is the determinative factor of chemoresistance in various types of cancers including CRC32,33, PRDM1 was assessed for its effects on formation of cancer stem cells (CSCs)." (PMID 33972671, 2021).